MCL1 (MCL1 apoptosis regulator, BCL2 family member)
Diseases named in the same sentence as MCL1 in open-access papers (continued):
Sharing a sentence is not in itself a finding about the gene and the disease.
glioma (continued). "In line with our analyses, BCL-xL and MCL-1 mRNA levels were higher expressed in GBM compared to lower grade gliomas and normal brain tissue." (PMID 35473984, 2022). "Gossypol (AT-101) tested in GBM treatment, binds to BH3 domains of Bcl-2, Bcl-xl, and Mcl-1, and is reported to efficiently inhibit in vitro and in vivo growth of glial tumors." (PMID 36309485, 2022). "Herein, we determined that the most abundantly expressed anti-apoptotic Bcl-2 family members, Bcl-xL and Mcl-1, are the most relevant in regulating patient-derived glioma stem cell survival." (PMID 36273072, 2022). "Recent research has shown that silencing MCL1 leads to inhibition of cell proliferation, thereby promoting apoptosis in glioma cells." (PMID 33607293, 2021). "In our study, we describe the novel finding that SD‐36 decreased Bim levels beyond their effects on reducing Mcl‐1 levels in sensitive human glioma cells, whereas Stattic clearly increased Bim levels in these cell lines." (PMID 34291563, 2021). "MCL1, an anti-apoptotic Bcl-2 family gene that promotes survival of glioma cells by preventing apoptosis, was found to be downregulated in both GBM cell lines." (PMID 34359676, 2021). "In TMZ-resistant glioma tissues, the expression levels of resistant marker proteins MCL-1 and MRP-1 were increased." (PMID 33106913, 2021). "Silencing of MCL1 promoted senescence and apoptosis in glioma cells by impairing the PI3K/AKT signaling pathway." (PMID 34783292, 2021). "We next determined the mechanisms by which SD‐36 induces a reduction in Mcl‐1 levels in glioma cell lines." (PMID 34291563, 2021). "Our results indicate that MCL-1 degradation in an HSF1-independent manner is an essential step for the modulation of apoptotic cell death brought about by KRIBB11 in glioma cells." (PMID 34299435, 2021). "In high-throughput sequencing results, we found that hsa_circ_0110757 of Mcl-1 was overexpressed in TMZ-resistant glioma patient tissues and cells." (PMID 33674567, 2021). "Further, Mcl‐1 suppression contributed to an increase in apoptosis induced by TMZ by SD‐36 in glioma cells because induced Mcl‐1 overexpression attenuated the increased rate of apoptosis induced by the combination." (PMID 34291563, 2021). "SD‐36 potently induced apoptosis in glioma cells along with a reduction in Mcl‐1 levels, which are critical for mediating the induction of apoptosis and enhancing TMZ‐induced apoptosis." (PMID 34291563, 2021). "Hsa_circ_0110757 was identified in TMZ-resistant glioma cells by high-throughput sequencing analysis and was derived from reverse splicing of myeloid cell leukemia-1 (Mcl-1) exons." (PMID 33674567, 2021). "Hsa_circ_0110757 was the most significantly overexpressed circRNA in TMZ-resistant glioma tissues, which was derived from the reverse splicing of Mcl-1 exons." (PMID 33674567, 2021). "The involvement of ER stress in indomethacin-induced Mcl-1 downregulation was reported in our previous study on glioma cells." (PMID 32545774, 2020). "Here, we found that Mcl-1 expression correlated with the presence of a super-enhancer region in glioblastoma models, providing an explanation why this protein is increased in gliomas." (PMID 32752193, 2020). "Herein, aspirin-induced H4 glioma cell apoptosis was accompanied by Mcl-1 downregulation and Noxa upregulation, as well as Bax/Bak mitochondrial distribution and oligomerization." (PMID 32545774, 2020). "The inhibition of Mcl-1 not only induces glioma cell apoptosis but also sensitizes glioma cells to therapeutic treatments." (PMID 32545774, 2020). "Our previous study reported that Akt inactivation through the action of ceramide and the consequence of Mcl-1/FLIP downregulation substantially contributed to indomethacin-induced glioma apoptosis." (PMID 31952288, 2020). "As the occurrence of MCL1 CN gain was relatively low in public datasets, we further validated this finding using RNA expression data in 510 TCGA low-grade glioma patients." (PMID 33747896, 2020).
glioma (continued). "ER stress inhibitor alleviated indomethacin-induced p38 hyperphosphorylation, Akt, dephosphorylation, Mcl-1/FLIP downregulation, caspase 3 activation, and glioma cell viability loss." (PMID 31952288, 2020). "The findings suggest that p38 represents an alternative machinery in mediating indomethacin-induced glioma apoptosis lying upstream of the PP2A/Akt/Mcl-1 and FLIP axis." (PMID 31952288, 2020). "We found that over-expression of Mcl-1 cDNA partially rescued from killing by the combination treatment, suggesting that Mcl-1 is both sufficient and necessary for the combination treatment to exert its anti-glioma effects." (PMID 32752193, 2020). "The first study to characterize RBP impact on BCL2 family mRNA localization demonstrated that HuR silencing in glioma cells results in a general shift of MCL1, BCL2, and BCLxL mRNA towards polyribosomes." (PMID 29361709, 2018). "Our previous study confirmed that miR-139 was downregulated in clinical gliomas and glioma cell lines, and miR-139 inhibits Mcl-1 expression and potentiates TMZ-induced apoptosis in glioma." (PMID 30170559, 2018). "It is also for this reason that other modalities or compounds are necessary to interfere with Mcl-1 levels in high grade gliomas." (PMID 30337641, 2018). "It has been demonstrated that Notch-1 promoted proliferation and survival of glioma cells through EGFR/Mcl-1 and mTOR signaling." (PMID 26824182, 2016). "We observed that the protein levels of Mcl-1 and survivin were further decreased when Sirt3 expression was knocked down in glioma cells subjected to hypoxia." (PMID 27270321, 2016). "Taken together, these observations are consistent with the confirmed targeting of MCL-1 3′UTR reporter constructs in glioma, ovarian and colorectal cancer cell lines." (PMID 26125439, 2015). "Wang reported that activated Notch up-regulated the anti-apoptotic protein activity of phosphorylated Akt and Mcl-1 and promoted the radiation resistance of glioma stem cells." (PMID 26599017, 2015). "While Mcl-1 is downregulated by combination treatment, it appears that increased levels of Noxa are critical to cellular death in glioma." (PMID 26044191, 2015). "For instance, CD133+ glioma CSCs express a high level of anti-apoptotic proteins Bcl-2 and Bcl-XL, and high expression of Mcl-1 correlates with resistance to the Bcl-2 inhibitor ABT-737 in glioma CSCs." (PMID 24823879, 2014). "WP1066 selectively inhibits the STAT3 pathway and reduces STAT3-driven expression of Bcl-2, Bcl-xL, and Mcl-1, triggering Bax activation and resulting in extended survival of xenogeneic glioma mouse models." (PMID 22431925, 2012). "Expectedly, RNAi-mediated downregulation of Mcl-1 in glioma cell lines and stem cells was found to increase sensitivity to ABT-737-induced apoptosis." (PMID 22431925, 2012). "Western blot analysis revealed that the changes of survivin, Bcl-XL, Bcl-2, and Mcl-1 protein in C6 glioma cells treated with 10 μmol/L of LY294002, or/and 5 μmol/L of tamoxifen for 24 h were similar as the changes of mRNA." (PMID 22046442, 2011). "Finally, to confirm the therapeutic efficacy of targeting the ROS1–JAK–STAT axis in KLC1-ROS1 fusion-harboring gliomas, the antitumor efficacies of lorlatinib, ruxolitinib, and the Mcl-1 inhibitor subtoclax, in combination with TMZ, were investigated." (PMID 38201436, 2023). "Finally, we determined BCL-xL and MCL-1 mRNA expression in different glioma subtypes and normal brain tissue using the publicly available REMBRANDT database." (PMID 35473984, 2022). "In addition, we explored the effects of these compounds on the viability of human glioma U87 MG cells and on the expression levels of Bcl-2 and Mcl-1 proteins." (PMID 36267274, 2022). "But the expression of c-FLIP and Mcl-1 was upregulated in carboplatin-resistant glioma cell lines." (PMID 35674307, 2022). "Therefore, the imbalance between Noxa and Mcl-1 towards the former will guide the apoptotic program in dipyridamole-treated glioma cells." (PMID 35054765, 2022).
glioma (continued). "C-FLIP and Mcl-1 are involved in carboplatin resistance in glioma cells." (PMID 35674307, 2022). "In addition, we found that in glioma tissues from the TCGA database, SAA1 levels were associated with a range of anti-apoptotic genes (Bcl-xl, BFL1, MCL1, BIRC5, and Fas) and pro-apoptotic genes (Bim, Bid, CASP9 and Apaf1)." (PMID 33854635, 2021). "In addition, it was suggested that c-FLIP and Mcl-1 were downregulated when treated with carboplatin in glioma cells was because of the increased activity of proteasome subunit alpha 5 (PSMA5)." (PMID 34065991, 2021). "Additionally, we have also identified a novel MCL1 amplification (found in 31% patients) as a potential independent biomarker for glioma (multivariate HR, 2.78; 95% CI, 1.53–5.08; P < 0.001), which was seldom reported in public databases." (PMID 33747896, 2020). "We found that the human H4 glioma cell-killing effects of aspirin involved mitochondria-mediated apoptosis accompanied by endoplasmic reticulum (ER) stress, Noxa upregulation, Mcl-1 downregulation, Bax mitochondrial distribution and oligomerization, and caspase 3/caspase 8/caspase 9 activation." (PMID 32545774, 2020). "Findings indicate that free of Bax from Mcl-1-mediated sequestration, promotion of Bax conformational change favoring mitochondrial translocation and oligomerization, and relief of caspase 8 inhibition are targets for indomethacin-induced glioma apoptosis." (PMID 31952288, 2020). "As speculated, patients with gain of MCL1 displayed significantly shorter overall survival irrespective of their clinical status, providing the first evidence of its prognostic value in glioma." (PMID 33747896, 2020). "On the other hand, the use of inhibitors of the HSF-1/HSP90/BAG3 pathway increases the antineoplastic effect of AT101, reactivating caspase-dependent apoptosis in the U252 and U343 glioma cell lines through a downregulation of Bcl-2 and Mcl-1 and an increase of Bax and mitochondrial dysfunction." (PMID 30486451, 2018). "In addition, IDH1 mutant gliomas were more sensitive for Bcl-xl inhibition, which was shown to be dependent on D-2HG, which lowers Mcl-1 expression in mutant gliomas compared to wild type gliomas thereby increasing sensitivity for Bcl-xl inhibition." (PMID 30242253, 2018). "Likewise, ionizing radiation has been shown to induce miR-193a-3p expression and promote apoptosis by directly targeting MCL1 in U251 glioma cells." (PMID 29361709, 2018). "Downregulation of MCL1 promotes temozolomide-induced apoptosis in gliomas." (PMID 26504803, 2015). "To examine whether down-regulation of Mcl-1 is sufficient to sensitize glioma cells for ABT263-mediated apoptosis, we performed knock-down experiments targeting Mcl-1 in LN229 glioblastoma cells." (PMID 26008975, 2015). "Inhibition of MCL-1 potentiates temozolomide-induced apoptosis in gliomas." (PMID 26036638, 2015). "MiR-153 is significantly down-regulated in glioma compared with normal brain tissues and decreases cell proliferation and increases apoptosis by targeting B cell lymphoma 2 (Bcl-2) and myeloid cell leukemia sequence 1 (Mcl-1) genes in glioma cell lines." (PMID 26124081, 2015). "Additionally, targeting of Mcl-1 using shRNA has been demonstrated to sensitize glioma stem cells to the small molecule inhibitor, ABT-737." (PMID 24213561, 2014). "Similar detailed biochemical and genetic studies analyzing cellular and molecular responses to RTK inhibition are still pending for glioma cells and derived tumors: Is the Bim/Mcl-1 rheostat important for determining sensitivity of GBM tumors to RTK inhibition?" (PMID 22431925, 2012). "Indeed over-expression of miR-15b results in cell cycle arrest in glioma cells, the miR-29 family targets Mcl-1, and let-7a targets caspase-3." (PMID 21283524, 2011).
glioma (continued). "In high-grade gliomas the activity of Bcl-2 family members is usually deregulated; in particular, these tumors display increased expression of the anti-apoptotic factors Bcl-2, Bcl-xL, and Mcl-1, and decreased expression levels of the pro-apoptotic protein Bax37." (PMID 36273072, 2022). "Moreover, Mcl-1 mRNA amounts increased from lower-grade gliomas to grade IV GBM." (PMID 34344865, 2021). "Immune-related pathways such as TNF signalling (IDH3B/G, MDH1, ACO2, SDHA, OGDHL) and JAK/STAT3 (PIAS2/3, PTPN2, AKT1/2, MCL1, CISH, AOX1) signalling are enriched in gliomas and play a critical role in their progression." (PMID 41007296, 2025). "The use of UMI-77, a substance that inhibits Mcl-1, enhances the effectiveness of TRAIL therapy in glioma cells by increasing TRAIL-induced apoptosis." (PMID 38566075, 2024). "Analysis of the TCGA glioma dataset reveals even a worsened survival rate for patients with high BCL-xL and MCL-1 gene expression." (PMID 35473984, 2022). "When glioma cells were treated with carboplatin, the protein levels of cellular FLICE-inhibitory protein (c-FLIP) and myeloid cell leukemia 1 (Mcl-1) were decreased, while apoptosis was inhibited." (PMID 35674307, 2022). "RNAi-mediated knockdown of STAT3 in human U251 glioma cells led to increased apoptosis via the suppression of transcriptional downstream targets of STAT3, such as Bcl-xL, Mcl-1, and survivin." (PMID 33498872, 2021). "Through many experiments, we found that hsa_circ_0110757, originating from myeloid cell leukemia-1 (Mcl-1) exons, was obviously overexpressed in TMZ-resistant and TMZ-sensitive glioma tissues and cells." (PMID 33674567, 2021). "Their active involvement in indomethacin-altered p38, Akt, Mcl-1, FLIP, caspase 3, and glioma cell viability was demonstrated by the reversal effects of PDTC and BAPTA-AM." (PMID 31952288, 2020). "Data on pharmacological inhibition related to oxidative stress, ER stress, free Ca2+, and p38 revealed that the axis of oxidative stress/ER stress/Ask1/p38/PP2A/Akt comprised an apoptotic cascade leading to Mcl-1/FLIP downregulation and glioma apoptosis." (PMID 31952288, 2020). "Previously, we showed that the ceramide/PP2A/Akt axis, which induces Mcl-1 and FLIP downregulation, is a COX-independent target for indomethacin and turns on the apoptotic program in glioma cells." (PMID 31952288, 2020). "The current findings indicate that the oxidative stress/ER stress/Ask1/p38 cascade contributes to indomethacin-induced glioma apoptosis, at least in part, by exerting an effect on the axis of PP2A/Akt/Mcl-1 and FLIP." (PMID 31952288, 2020). "Instead, the demise of Mcl-1 and FLIP expression involving Akt inactivation and Bax mitochondrial translocation and oligomerization led to substantial glioma apoptosis." (PMID 31952288, 2020). "Our previous study identified an apoptotic cascade of the axis of PP2A/Akt/Mcl-1 and FLIP in indomethacin-induced glioma apoptosis." (PMID 31952288, 2020). "Akt is crucial for transcriptional activation of Mcl-1 and FLIP and its constitutive activation predicts poor prognosis in glioma patients." (PMID 31952288, 2020). "The ceramide/PP2A/Akt axis and consequences of Mcl-1 and FLIP downregulation constitute the mode of action in indomethacin-induced glioma apoptosis." (PMID 31952288, 2020). "Previously, we reported the role of an apoptotic axis triggered by ER stress, which led to p38 activation and Akt inactivation, resulting in Mcl-1 and FLIP downregulation in indomethacin-treated glioma cells." (PMID 32545774, 2020). "Data from mechanistic studies further indicated oxidative stress/ER stress/Ask1/p38 cascade is an alternative regulator of the PP2A/Akt axis, resulting in Mcl-1 and FLIP downregulation and eventually glioma apoptosis." (PMID 31952288, 2020). "The multikinase inhibitor sorafenib is also a Mcl-1 inhibitor, useful in sensitization to ATB-737 treatment, showing a higher apoptosis induction in LN229 and U87 glioma cells." (PMID 30486451, 2018).
glioma (continued). "The ARE-binding protein HuR (human antigen R) has been reported to bind to the 3′ UTRs of MCL1, BCL2, and BCLxL, stabilizing their RNA, and increasing their expression in glioma." (PMID 29361709, 2018). "Our observations suggest that L-asparaginase sensitizes glioma cells to ABT263 in part by modulation of Noxa, Mcl-1 and Usp9X levels." (PMID 27172899, 2016). "Further mechanistic study examined the expression of Bcl-2 family members, including Bcl-2, Mcl-1, Bax and Bim, in SPHK1-overexpressing glioma cells and revealed that only pro-apoptotic Bim was downregulated by SPHK1." (PMID 21625639, 2011). "Using a pooled CRISPR/Cas9 knockout screening approach on 65 pediatric and 10 adult high-grade glioma (HGG) cell lines, myeloid cell leukemia 1 (MCL1) emerged as a key antiapoptotic gene essential in pediatric but not adult gliomas." (PMID 39846250, 2025). "We show that the anti-apoptotic proteins BCL-XL and MCL-1 both protect against cell death across all glioma tumours, regardless of genetic features." (PMID 39572533, 2024). "We also observed that in both glioma cell lines, TSAIII induces cell death and mitochondrial dysfunction, consistent with observed increases in the protein expression of cleaved-caspase-3, cleaved-caspase-9, cleaved-PARP, cytochrome c, and Mcl-1." (PMID 36611961, 2022). "However, ABT-737 was less efficient in glioma stem cells with high myeloid cell leukemia 1 (MCL1) expression, and sorafenib targeting MCL1 synergized with ABT-737 to trigger apoptotic cell death in glioma cells." (PMID 35990696, 2022). "Radiation induces the secretion of exosomes by glioma cells containing proteins involved in numerous crucial signaling pathways including JAK/STAT, as well as proteins such as ribophorin II, which signal through STAT3 to promote anti-apoptosis via Mcl1." (PMID 33498872, 2021). "In the present study, we demonstrated that an exclusive treatment with KRIBB11 effectively induces apoptosis in A172 glioma cells through acceleration of MCL-1 degradation, which is not accompanied by any alteration of HSF1 activity." (PMID 34299435, 2021). "Thus, SD‐36 effectively impedes the growth of glioma xenografts by reducing STAT3 and Mcl‐1 levels and enhancing apoptosis in vivo." (PMID 34291563, 2021). "Thus, the molecular mechanism of carboplatin resistance occurs through the regulation of Mcl-1 and c-FLIP by the elevation of Nrf2-dependent PSMA5 expression in glioma cells." (PMID 34065991, 2021). "Investigations of pharmacological inhibition related to oxidative stress, ER stress, free Ca2+, and p38 revealed that the axis of oxidative stress/ER stress/Ask1/p38/PP2A/Akt constitutes an apoptotic cascade leading to Mcl-1/FLIP downregulation and glioma apoptosis." (PMID 31952288, 2020). "Also, depletion of Mcl-1 by mTOR inhibitors increase vulnerability to PARP inhibitors, providing additional therapeutic options for glioma." (PMID 33747896, 2020). "After a thorough literature search, we noticed that the prognostic significance of MCL1 in glioma might be neglected as many cohort studies did not specifically cover or focus on MCL1 gene-level amplification." (PMID 33747896, 2020). "The action of Mcl-1/Bak axis on TMZ-induced cell death of BRCC3-KD glioma cells is not yet known." (PMID 25337721, 2014). "We also show that upon TMZ treatment Mcl-1 expression is not modified at the transcriptomic level but at the protein level.This suggests that targeting Mcl-1 either by competitive inhibitors of its interaction with Bak or by promoting its degradation is a potentially important target in glioma." (PMID 24811082, 2014). "Hyp cytotoxicity was low in human U87 MG glioma, similar to that of ABT263, where Goss exerted sufficient cytotoxicity, suggesting that Hyp acts primarily on Bcl-2, but not on Mcl-1 protein." (PMID 36267274, 2022).